IL1B (interleukin 1 beta)
Diseases named in the same sentence as IL1B in open-access papers (continued):
Sharing a sentence is not in itself a finding about the gene and the disease.
benign prostatic hyperplasia (6 papers, 2017 to 2025). A non-cancerous nodular enlargement of the prostate gland. "Thus, the pathogenic role of HIF-1α in prostatic hyperplasia gains extra support by the observed elevation of TNF-α and IL-1β by testosterone." (PMID 30154949, 2018). "GHRH antagonists also reduced prostate size and expression of inflammatory mediators, such as IL-1β, NF-κB p65, and COX-2, in rat prostatic hyperplasia." (PMID 37649486, 2023). "Moreover, CP/CPPS patients exhibit markedly decreased zinc levels in seminal plasma, and a reduction in zinc levels is typical for PCa and benign prostate hyperplasia (BPH), which has been shown to skew the inflammatory reaction by increasing the production of IL‐1B and TNFα." (PMID 36321189, 2023).
bone marrow fibrosis (6 papers, 2022 to 2025). "Upregulation of PAOX was shown in the nucleus pulposus (NP) cells during the degeneration of intravertebral disks caused by IL-1β, as well as in patients with primary myelofibrosis." (PMID 38994986, 2024). "In this regard, two groups have recently demonstrated that genetic ablation or pharmacological inhibition of IL-1β or IL-1 receptor 1 attenuates clonal expansion and bone marrow fibrosis and osteosclerosis in Jak2V617F MPN mouse models." (PMID 38035089, 2023). "Exogenous administration of IL-1β enhances myeloid cell expansion and accelerates the development of bone marrow fibrosis in heterozygous Jak2V617F mice." (PMID 36100596, 2022).
chronic rhinosinusitis (6 papers, 2012 to 2024). Chronic form of sinusitis. "IL-1β is expressed in NPs, and P. aeruginosa is a common culture isolate in chronic rhinosinusitis (CRS)." (PMID 35163151, 2022). "We found that ACE2 messenger RNA levels were positively correlated with pro-inflammatory cytokines (tumour necrosis factor-α (TNF-α) and IL-1β) and negatively correlated with eosinophil-related chemokines (eotaxin-3) in chronic rhinosinusitis patients." (PMID 33928889, 2021). "Interestingly, when using a variable chronical rhinosinusitis endotype analysis, IL-1β was most often the choice." (PMID 34208325, 2021). "IL-1β and TNF-α play a major role in the progression of acute sinusitis and that IL-3 dominates the cytokine profile in chronic sinusitis—leading to the coordinating effects of a variety of inflammatory cells." (PMID 38248349, 2024). "In chronic rhinosinusitis patients, TNF-α and IL-1β messenger RNA levels were positively correlated with ACE2 (r = 0.4971 for TNF-α and r = 0.3082 for IL-1β)." (PMID 33928889, 2021). "A different study analyzed patients with chronic rhinosinusitis with polyps only, and one of the clusters showed an increase in IL-1β, but the other author did not obtain statistically significant evidence of IL-1β value being higher in at least one of the analyzed clusters." (PMID 34208325, 2021). "In contrast, the non-eosinophilic chronic rhinosinusitis patients tended to show higher ACE2, TNF-α and interleukin (IL)-1β messenger RNA levels than controls, but the difference was not significant." (PMID 33928889, 2021).
colorectal adenoma (6 papers, 2010 to 2019). An adenoma that arises from the colon or rectum. "It has been reported that the transcription of the metalloproteinase gene is positively regulated by cytokines and growth factors such as interleukins (IL1β) or TNFα suspected to be associated with the formation of colorectal adenoma in humans." (PMID 22735354, 2012). "The aims of this study were to examine whether serum concentrations of IL-1β, IL-2, IL-8, IL-10, IL-12p70, GMCSF, IFNγ, and TNFα were associated with flavonol intake or could predict colorectal adenoma recurrence." (PMID 20924374, 2010). "Furthermore, the gene and protein expression of IL-1β is higher in colorectal adenoma and adenocarcinoma relative to normal colon tissue." (PMID 20924374, 2010). "In the current study, we examined serum concentrations of eight cytokines (IL-1β, IL-2, IL-8, IL-10, IL-12p70, GMCSF, IFNγ, and TNFα) in relation to flavonol intake and colorectal adenoma recurrence and found none to be associated with flavonol intake and with colorectal adenoma recurrence." (PMID 20924374, 2010).
dermatomyositis (6 papers, 2013 to 2025). Dermatomyositis (DM) is a type of idiopathic inflammatory myopathy characterized by evocative skin lesions and symmetrical proximal muscle weakness. "In dermatomyositis, IL1B and IL18 protein levels are elevated in serum, and gene expression levels are also increased in muscle tissue." (PMID 40080076, 2025). "Yin Xi’s research group reported that compared to healthy controls, patients with polymyositis (PM) and dermatomyositis (DM) showed elevated levels of NLRP3, IL-1β, and IL-18 mRNA in muscle fiber tissues, as well as increased expression of NLRP3 and caspase-1 p20 protein subunit." (PMID 39723212, 2024).
Flavivirus Infections (6 papers, 2011 to 2025). Infections with viruses of the genus FLAVIVIRUS, family FLAVIVIRIDAE. "Both species exhibited a balanced immune response, with TNF-α and IL-1β playing key roles in inflammation, while IL-10 and IL-13 were prominent in immunomodulation—patterns that are consistent with other flavivirus infections." (PMID 40143314, 2025). "Taken together, these observations along with those made in this study identify IL-1β as a key host restriction factor in immunity against Flavivirus infection." (PMID 23209411, 2012). "Following flavivirus infection activated glial cells release TNF, IL1β, IL6, and RANTES, all of which promote bystander damage to neurons." (PMID 28873445, 2017).
fracture (6 papers, 2013 to 2022). "For example, if bone fracture combined with TBI is found to cause a particularly significant increase in IL-1β expression in the early stages post-injury, as found in mice, therapies such as IL-1 receptor antagonists may prove to be more effective in this form of TBI." (PMID 27117191, 2016). "In order to determine if hip fracture surgery was associated with changes in serum cytokine levels, IL-6, TNF-α, IL-1β, and IL-10 levels in blood were quantified 1, 3, and 7 days after hip fracture and surgery (including sham-operated controls)." (PMID 24163505, 2013). "The myocardial activation of the NLRP3 inflammasome, inducing the cleavage mature IL-1β was further shown by our group after multiple trauma and isolated bone fracture, and was also considered to contribute to the development of post-traumatic myocardial damage and secondary cardiac injury." (PMID 36131923, 2022). "However, the alterations in cardiac glucose and fatty acid transporters following bone fracture were recently demonstrated to be induced by pro-inflammatory mediators such as HMGB1, IL-1β, IL-6 and TNF, all of which have been shown to be elevated following hip fracture in the present study." (PMID 36131923, 2022). "Other inflammatory cytokines such as interleukin-1β (IL-1β), tumour necrosis factor-α (TNF-α), and granulocyte-macrophage colony-stimulating factor (GM-CSF) have been shown to be elevated in the systemic circulation following peripheral injury (e.g. bone fracture) as well as in TBI." (PMID 27117191, 2016). "However, in C5aR2−/− mice, the concentrations of IL-1β, tumour necrosis factor (TNF) α and monocyte chemoattractant protein-1 (MCP-1) were significantly elevated after isolated fracture, indicating a pulmonary inflammatory response after bone fracture even in the absence of thoracic trauma." (PMID 29070810, 2017).
gastric diseases (6 papers, 2018 to 2025). "Genotype and haplotype allelic distribution of IL-1B polymorphism in clinical patients with gastric disease and healthy individuals." (PMID 32494282, 2020). "However, in the H. pylori seropositive patients with gastric diseases, risk was increased 20% for IL-1B-511 CC haplotype as compared to H. pylori seronegative carrying 14.3% CT haplotype." (PMID 32494282, 2020). "Since the allele 2 is associated with increased production of the IL-1B, which limits the amount of gastric acid and that acid reduction is favorable for bacterial colonization, the allele 2 can play a role in the development of gastric diseases with the presence of H. pylori." (PMID 30320011, 2018). "In the present study, we focused on age, gender, H. pylori, IL-1B-511 genotypes, and IL-1β mRNA level which may participate in the formation of gastric pathology and TCM syndrome in subjects with H. pylori-related gastric diseases." (PMID 32382299, 2020). "Both IL-1B-511 and 31 positions were not equally responded for gastric diseases development." (PMID 32494282, 2020).
gonococcal infection (6 papers, 2016 to 2024). "We had previously found that cervical secretion of IL-1β in asymptomatic gonorrhea patients were much less compared to that in symptomatic patients." (PMID 33633700, 2021). "Our group had previously found out that in females, asymptomatic gonococcal infections correlate with higher serum progesterone (P4) levels and lower IL-1β levels in cervical secretions." (PMID 33633700, 2021). "In addition to CXCL8 and IL1B, we also observed multiple genes previously shown to be involved in responses to gonococcal infections, including PTGS2 and ICAM1." (PMID 38976720, 2024). "In the murine infection model, P4 (1 mg/day) inhibited the inflammatory effects induced by gonococcal infections which led to decreased neutrophil infiltration, reduced polymorphonuclear neutrophils (PMNs) numbers, IL-1β, TNF-α, and IL-6 levels in vaginal secretions." (PMID 33633700, 2021). "However, when we looked at transcript level, we showed a sizable induction of IL-1β RNA upon gonococcal infection." (PMID 27803513, 2016). "However, when total mRNA levels of pro-IL-1β were assessed by qPCR, we observed that pro-IL-1β RNA levels were highly induced in response to gonococcal infection, indicating that Ngo is able to trigger the signaling pathway to start pro-IL-1β synthesis." (PMID 27803513, 2016).
graft versus host disease (6 papers, 2008 to 2023). An immune system disorder that occurs after allogeneic hematopoietic stem cell transplant and is a reaction of donor immune cells against host tissues. "We have also reported an association between IL-1β, EBV, and graft-versus-host disease in immunosuppressed children with allogeneic hematopoietic progenitor cell transplantation." (PMID 36675141, 2023). "Also, uric acid promotes DC activation, in an IL-1β dependent fashion, and contributes to the onset of graft-versus-host disease." (PMID 26075613, 2015). "We also found that IL-1β, IL-2, IL-6 and IL-8 were significantly increased in episodes in which multiple viruses were simultaneously detected, and samples positive for EBV DNA and graft-versus-host disease had a further increase of IL-1β and IL-8." (PMID 36014102, 2022).
hemorrhagic cystitis (6 papers, 2015 to 2024). Inflammation of the bladder resulting in bloody urine. "The hemorrhagic cystitis induced by CYP administration was also associated with a marked increase of cytokine IL-1β." (PMID 26154141, 2015). "Cyclophosphamide‐induced severe hemorrhagic cystitis is detected with significantly elevated IL‐1B cytokine expression in vivo." (PMID 39723046, 2024). "The hemorrhagic cystitis induced by IFOS administration also caused a marked increase of TNF-α and IL-1β cytokines when compared with the Sham group." (PMID 35625456, 2022). "Increasing inflammatory mediators such as TNF-α, IL-6, and IL-1β in hemorrhagic cystitis will further aggravate the inflammatory response." (PMID 34804174, 2021). "Another potential approach to treat chemotherapy-induced hemorrhagic cystitis is to administer IL-412, a potent anti-inflammatory cytokine known to antagonize the IL-1β, TNFα and IL-6 pathways." (PMID 30733505, 2019). "Other candidate drugs for ifosfamide-induced hemorrhagic cystitis have also been shown to specifically target the IL-1β-TNFα-IL-6 pathway." (PMID 30733505, 2019). "The present study provided evidence that IPG exerts anti-inflammatory and antioxidant activities which modulate the hallmarks underlying hemorrhagic cystitis, as it reduced the levels of TNF-α, IL-1β, MDA, and C-reactive protein, as well as increasing SOD levels and reducing edema and hemorrhage." (PMID 35625456, 2022). "Candidate drugs targeting the inflammatory IL-1β, TNFα and IL-6 triad and/or promoting antioxidant responses show promise for ameliorating hemorrhagic cystitis but have not progressed beyond preclinical testing." (PMID 30733505, 2019). "Besides effects on the IL-1β, TNFα and IL-6 triad, IPSE may also mediate critical gene expression changes in chemokines during ifosfamide-induced hemorrhagic cystitis." (PMID 30733505, 2019).
hepatitis B (6 papers, 2020 to 2025). "Similarly in other studies, higher concentrations of plasma circulating cytokines IL-18 and IL-1β were observed in hepatitis B patients." (PMID 34161370, 2021). "However, some studies found that IL-1β inhibited long-term potentiation in the hippocampus in inflammatory responses elicited by LPS or hepatitis B vaccination, suggesting complicated effects of IL-1β on neural excitability under different pathological conditions." (PMID 38438808, 2024). "Hepatitis B virus infection induces inflammatory cytokine secretion (e.g., TNF-α, IL-1β, IL-6), which promotes bone resorption and reduces bone formation by activating osteoclasts and inhibiting osteoblast function." (PMID 41404370, 2025). "IL8 and IL1B play a crucial role in protection against both hepatitis B and S. pneumoniae, and our findings of an increase in PCV13 antibody response in children vaccinated against hepatitis B might be due to of an increased activation of the mucosal immune system." (PMID 32277105, 2020).
hyperhomocysteinemia (6 papers, 2016 to 2022). A serious metabolic condition caused by mutations in the MTHFR gene, medications, or nutritional deficiency. "We hypothesize that the high fat diet (HFD) causes dysbiosis, systemic inflammation, and hyperhomocysteinemia (HHcy) in susceptible individuals, which subsequently elevate inflammatory cytokines such as IL-1β, IL-6, IL-17, and tumor necrosis factor alpha (TNF-α)." (PMID 32973741, 2020). "Several studies have also shown that proinflammatory cytokines, such as tumor necrosis factor-alpha (TNF-α) and interleukin-1β (IL-1β), are increased in endothelial cells, retinal cells, and microglia by hyperhomocysteinemia." (PMID 35832851, 2022). "The hyperhomocysteinemia not only induced the secretion of Il-1β, Il-6, RANTES by monocytes, but also promoted inflammation via the TNFα induction, and subsequent MEF2 and NF-κB transactivation." (PMID 34771080, 2021). "A pathway analysis model showed that hyperhomocysteinemia and HDD90 along with LBP and IL1β showed a significant cumulative effect on alcohol withdrawal in Gr." (PMID 33374263, 2020).
hyperthyroidism (6 papers, 2020 to 2023). Overactivity of the thyroid gland resulting in overproduction of thyroid hormone and increased metabolic rate. "However, Asians show different genetic polymorphisms for hyperthyroidism risk: IL-1α at 889 C/T, IL-1β at 511 C/T, IL-6 at 174 G/C, IL-6 at 572 G/C, and IL-10 at 1,082 A/G polymorphisms." (PMID 34567510, 2021). "The results showed that compared with those in the control group, the mRNA expression levels of Tnf-α, Il-1β, and Il-6 in the hyperthyroidism group were significantly increased compared with those in the controls." (PMID 36139036, 2022). "Elevated levels of pro-osteoporotic cytokines including IL-1β have been found in patients with different forms of hyperthyroidism." (PMID 32477265, 2020). "The findings showed that hesperidin significantly modulated hyperthyroidism deteriorations, this was evidenced by a remarkable decline in serum T4, FT4, T3, FT3, TNF-α, IL1β-, IL4-, IL-6, and IL-10 levels, with a minor increase in TSH and significant raise in CD4+ level." (PMID 37020549, 2023).
invasive breast carcinoma (6 papers, 2007 to 2024). A carcinoma that infiltrates the breast parenchyma. "The association between TIBs and IL-1β persists in invasive breast cancer, with strong tumor IL-1β expression correlating with poor outcomes in invasive disease." (PMID 39801513, 2024). "Another study indicated that the inhibition of the NLRP3 inflammasome stimulated the recruitment and activation of Natural Killer cells in invasive breast cancer model, independently of IL-1β and IL-18 signaling." (PMID 39433537, 2024). "Stromal OSM expression was 5.9-fold higher in invasive breast cancer compared to normal breast samples, and stromal IL-1β was 5.4-fold higher in invasive breast cancer compared to normal samples." (PMID 31007849, 2019). "The presence of IL-1β and IL-1α in tumor cells in patients with invasive breast cancer has also been described." (PMID 27391324, 2016). "IL-1β was previously shown to be strongly expressed in high-grade invasive breast carcinoma as compared with in situ ductal carcinoma or benign lesions." (PMID 17261184, 2007). "To assess the clinical relevance of this synergistic interaction between OSM and IL-1β, we analyzed the stromal expression patterns of OSM and IL-1β in both normal and invasive breast cancer patient data using the Finak Breast Stromal dataset obtained from OncomineTM." (PMID 31007849, 2019). "A study that examined human tissue extracts reported higher IL1B levels in invasive breast carcinoma compared to non-invasive breast tumors." (PMID 28143606, 2017). "In this study, we investigate the role of TIB induced activation of the IL-1β-NFκB signaling axis in TNBC cell lines, and explore the relationship between TIB, IL-1β, and clinical outcomes in hormone receptor negative (HR−) DCIS and invasive breast cancer." (PMID 39801513, 2024).
lung squamous cell carcinoma (6 papers, 2022 to 2024). "By contrast, KRAS/CCL2/IL1B expression did not impact the survival of patients with squamous cell lung carcinoma (a tumor with low KRAS mutation frequency) (upper right)." (PMID 35327394, 2022).
muscular dystrophy (6 papers, 2017 to 2025). Muscular dystrophy (MD) refers to a group of more than 30 genetic diseases characterized by progressive weakness and degeneration of the skeletal muscles that control movement. "A recent study investigating the adipogenic potential of fibro-adipogenic muscle progenitor cells isolated from patients with muscular dystrophy supported our findings by demonstrating that IL1B stimulated macrophages inhibited adipogenesis of these cells." (PMID 33971957, 2021). "In muscular dystrophy, chronic inflammation is driven by pro-inflammatory cytokines such as TNFα, IL1α, and IL1β." (PMID 34439837, 2021). "The present study suggests that the IL-1β/Jagged1 pathway will be a new therapeutic target to ameliorate exacerbation of muscular dystrophy in a dystrophin-independent manner." (PMID 29194448, 2017). "The IL1α and IL1β signaling pathway should be further investigated in muscular dystrophies models." (PMID 34439837, 2021). "The IL-1β/Jagged1 pathway may be a new therapeutic target to ameliorate exacerbation of muscular dystrophy in a dystrophin-independent manner." (PMID 29194448, 2017).